PDGFB (platelet derived growth factor subunit B)
Diseases named in the same sentence as PDGFB in open-access papers (continued):
Sharing a sentence is not in itself a finding about the gene and the disease.
tumor (continued). "Although the role of the PDGFB/PDGFRB axis in BC progression is still a subject of debate, PDGFRB overexpression was correlated with the acquisition of vascular-like functional properties of TNBC, suggesting its involvement in tumor aggressiveness." (PMID 32143514, 2020). "Therefore, this indicates the diverse role of PDGFB and PDGFR beta in facilitating tumor angiogenesis and progression at different cellular levels in TME." (PMID 32855630, 2020). "IHC staining with a pan-TRK antibody showed positive signal in Bcan-Ntrk1-induced tumors and not in control PDGFB-induced tumor." (PMID 29654229, 2018). "To ascertain the tumor-suppressive activity of IDH1R132H in vivo, we first established subcutaneous tumor growth of mouse astrocyte NA1 that had been transduced with luc–PDGFB, which expresses luciferase and platelet-derived growth factor B (PDGFB) upon P2A cleavage." (PMID 30416682, 2018). "In addition, recent studies have shown that tumour cells strongly promote blood vessel formation by secreting a diversity of angiogenic factors, such as VEGFA, PDGFB, bFGF and EGF8." (PMID 30584257, 2018). "Meanwhile, the PDGFB/H3K27M NSCs grew faster than the PDGFB/H3K27wt cells, which made the PDGFB/H3K27M NSCs could generate the larger tumor when implanted to the pons of the mice." (PMID 29118968, 2017). "Thus, we have demonstrated that EZH2 and BET proteins activity were required for the growth of PDGFB/H3K27M NSCs, inhibition of these two group of proteins showed an impressive interfere in tumor progression." (PMID 29118968, 2017). "PTN is not an oncogene on its own, but potentiates tumor initiation induced by e.g. PDGFB by augmenting Akt activation, leading to enhanced proliferation of neural progenitor cells." (PMID 27806344, 2016). "PDGFB and VEGFA were angiogenic factors and mediated tumor growth, angiogenesis and metastasis." (PMID 27833078, 2016). "Taken together, data from Rac1 flox/flox PDGFB-iCreER animals provided a second line of evidence that tumor growth and angiogenesis in vivo does not normally depend on Rac1." (PMID 20339539, 2010). "Experiments using the hypomorphic PDGFB-ret/ret mouse model, which expresses a truncated form of PDGF-B, lacking the C-terminal retention motif, resulted in impaired tumor angiogenesis and reduced pericyte coverage implying PDGF-BB/PDGFRβ as a promising, potential therapeutical target." (PMID 38980580, 2024). "Moreover, we found that the tumor tissue of muscone-treated mice expressed lower amounts of the proangiogenic factors VEGFA and PDGFB than did control mice, which potentially explained the rise in pericyte and BM coverage within tumor vessels of muscone-treated mice." (PMID 38898449, 2024). "In summary, our findings demonstrate a protumorigenic function of IL-1β in PDGFB-driven mGBM and show that blocking IL-1β signaling decreases inflammatory monocyte recruitment, MG abundance, and the frequency of exhausted CD8+ T cells, prolonging survival of tumor-bearing mice." (PMID 37733448, 2023). "On the other hand, in OSCC, tumor progression and metastasis are also sustained by the presence of hypoxia-inducible factor (HIF) and related genes induced by hypoxia, such as VEGF, interleukin 1A (IL-1A), endothelin 1, platelet-derived growth factor B (PDGFB) and erythropoietin (EPO)." (PMID 35890188, 2022). "Primary tumor growth was not affected by the lack of platelet-derived PDGFB." (PMID 35454853, 2022). "Notably, PDGFB confers a tumorigenic phenotype to human tumor cells bearing PDGFBR but not to cells devoid of receptors." (PMID 34362454, 2021). "Indeed, we found significantly higher numbers of Olig2+ cells outside the tumor bulk in PDGFB + DLK-A brains compared with controls, indicating that DLK-A may drive invasive tumor growth." (PMID 32205867, 2020). "Besides the crosstalk with CAFs, PDGFR beta in stromal fibroblasts may mediate PDGFB-induced TAM recruitment, thus implicating a role of PDGFR beta in tumor stroma to facilitate tumor progression." (PMID 32855630, 2020).
tumor (continued). "Indeed, YFP–IDH1R132H transduction failed to inhibit PDGFB-driven orthotopic tumor growth, resulting in similar bioluminescent readings in reference to the control." (PMID 30416682, 2018). "Although the contribution of PdgfB in tumour genesis is not fully clarified, the co-expression of PdgfB and its receptors has been described in many tumours, and autocrine PdgfB stimulation in these tumours has been suggested." (PMID 19812696, 2009). "Similarly, PDGFB, a master regulator of vasculogenesis during development and tumorigenesis, is known to promote human MSC proliferation and migration and regulate MSC recruitment and differentiation into a pericyte phenotype in tumors, thereby enhancing tumor angiogenesis." (PMID 28275008, 2017). "Additionally, recent research indicates that PDGFB-based nanocomposites may enhance the movement and infiltration of natural killer cells, macrophages that exhibit an M1 phenotype, and CD8+ T cells, thereby strengthening antitumor immune response and curtailing tumor growth." (PMID 38577601, 2024). "However, to our knowledge, there is no study directly evaluating the serum PDGFB level in RCC in comparison to a healthy control and across different tumor stages." (PMID 37047421, 2023). "Based on these observations, we hypothesized supplementing stroma-derived factors, such as IL-1β, could restore PDGFB-driven (PN), but not Nf1-silenced (MES), tumor cell production of MCPs." (PMID 37733448, 2023).
cancer (97 papers, 2009 to 2026). A tumor composed of atypical neoplastic, often pleomorphic cells that invade other tissues. "that fusion of the PCC-derived exosomes by PSCs leads to the activation of the Lin28B/let-7/HMGA2/PDGFB-related pathway, which is normally associated with increased production of PDGFB in cancer cells and inhibits itself through miR let-7 expression." (PMID 37287924, 2023). "However, irregularities in the signaling pathway of PDGFB are linked to the onset and advancement of cancer by fostering cell proliferation, stimulating the formation of new blood vessels, and increasing the invasive potential of cancerous cells." (PMID 38577601, 2024). "PDGFB is a growth factor associated with the metastasis of various types of human cancer." (PMID 26151573, 2015). "Moreover, ECM deposition, the amount of cancer-associated fibroblasts and TGFβ signaling were all reduced in tumors from mice with platelet-specific deletion of PDGFB, demonstrating the significant contribution of a platelet-derived factor to ECM remodeling in tumors." (PMID 35454853, 2022). "We found that four genes (EPHA3, PDGFB, PDGFRB, and GNG2) are implicated in cancer cell migration, invasion, and angiogenesis." (PMID 38233802, 2024). "Platelet derived growth factor (PDGFB) overexpression is observed in many cancers, contributing to cell proliferation, angiogenesis, migration, and invasion." (PMID 38339062, 2024). "In conclusion, cancer cell-derived PDGFB can mediate mTORC1 signalling pathway activation in ccRCC, further consolidating the link between the KLF6-PDGFB axis and the mTORC1 signalling pathway activity in ccRCC." (PMID 37047421, 2023). "Accordingly, PDGFB expression in cancer cells was significantly upregulated by IL6 and TGFB1 in vitro." (PMID 37658364, 2023). "Based on this, we fabricated a PDGFB targeting and biodegradable FePt alloy assembly for MRI-guided chemotherapy and starving-enhanced chemodynamic therapy of cancer using PDGFB targeting, pH-sensitive liposome-coated FePt alloys, and GOx (pLFePt-GOx)." (PMID 35672821, 2022). "The miR‐363‐5p deficiency promoted metastasis via facilitating PDGFB expression, leading to the overactivity of PDGF signaling in cancer cells." (PMID 34058065, 2021). "Most recently, it was further shown that specific targeting of PDGFR beta kinase activity in TME inhibited cancer growth and vascularization in cancers with high PDGFB expression such as LLC." (PMID 32855630, 2020). "High levels of PDGFA and PDGFB in CRC tissues were shown to correlate with poor cancer prognosis as well." (PMID 32316138, 2020). "Depletion of PDGFB significantly suppressed the proliferation, invasion and migration of cancer cells." (PMID 32330901, 2020). "In pancreatic cancer, the protein Lin28B in cancer cell-derived exosomes is transformed into these neighbor cancer cells to activate the Lin28B/let-7/HMGA2/PDGFB signaling pathway, promoting interaction with PSCs to enhance their migration to micro-metastatic sites." (PMID 37173915, 2023). "Herein, we fabricated a PDGFB targeting, biodegradable FePt alloy assembly for magnetic resonance imaging (MRI)-guided chemotherapy and starving-enhanced chemodynamic therapy for cancer using PDGFB targeting, pH-sensitive liposome-coated FePt alloys, and GOx (pLFePt-GOx)." (PMID 35672821, 2022). "Co-culture of melanoma cells with endothelial cells composing the abluminal surface of blood vessels, was demonstrated to induce the expression of genes linked to cancer cell migration (CCL2, ICAM1), cancer progression (TRAF1, SERPINB2) or stem cell properties (PDGFB; CFDP1)." (PMID 34604096, 2021). "These endothelial cells promoted cancer cell proliferation by secreting platelet-derived growth factor subunit B (PDGFB), which was stimulated by cancer cell-secreted vascular endothelial growth factor (VEGF), fibroblast growth factor 12 (FGF12), pleiotrophin (PTN) and neurofibromin 1 (NF1)." (PMID 24977105, 2012).
cancer (continued). "However, whether cancer cell-derived PDGFB is also able to activate mTORC1 activity in KLF6-depleted cells has remained unclear." (PMID 37047421, 2023). "However, the decreased expression of PDGFB demonstrated a good prognosis and potentially could be a promoted cancer factor." (PMID 34301211, 2021). "Along with an increased PDGFRb expression as in CAFs, another study demonstrated that PSCs are preferentially trafficked to metastatic sites under the influence of PDA-EVs, via activation of the PDGFB pathway in distant cancer cells, hypothesizing that PDGFB could act as a chemokine to attract PSCs." (PMID 34207163, 2021). "Interestingly, the expression levels of four genes (PDGFB, CCND2, CTF1, IL7R) identified in the current study were strongly associated with STAT3 activation, clinical outcome of LUAD patients and drugs sensitivity across cancer cell lines in GDSC." (PMID 34301211, 2021). "Analysis of mRNA expression in TCGA paired samples revealed notably enhanced levels of LDHA, SHC1 and CDKN3 in cancer tissues compared to adjacent tissues, whereas PCSK9, BTK, CAV2 and PDGFB showed significantly reduced expression." (PMID 40182622, 2025). "During this process, cancer cells secrete pro-angiogenesis factors, namely VEGFA, and PDGFB, which accelerate their progression." (PMID 35292059, 2022). "PDGFB and dimer protein PDGF‐BB is an important lymphangiogenic factor and contributes to cancer lymphatic metastasis by stimulating MAP kinase activity." (PMID 34058065, 2021). "The top three growth factors with strong correlations with OSM in most cancers were HGF, PDGFB, and TGFB1." (PMID 34702277, 2021). "PDGFB, FN1, and VEGFA were the common genes involved in the regulation of cell adhesion, response to wounding, and pathways in cancer." (PMID 34606420, 2021). "DGIdb mining identified celecoxib, axitinib, and vinblastine, which interact with DDIT3, PDGFB, and JUN, respectively, with minimal interactions with other genes and proven anti-cancer effects." (PMID 27821810, 2016). "Moreover, GEPIA analysis of TCGA data showed that PDGFB and PDGFRB were significantly overexpressed in various types of human cancers." (PMID 37307823, 2024). "We found that the positive feedback loop of PDGFB signaling and IL6 signaling between cancer cells and CAFs could substantially benefit the immune-suppressive stroma." (PMID 37658364, 2023). "Of the oncogenes, three are translocated cancer genes (CBFA2T3, PDGFB and PRDM16)." (PMID 33711952, 2021). "Indeed, we found that miR-146a over-expression reduced expression of several cytokines and growth factors with a known role in cancer development; IL-8, IL-23A, CCL5, CSF-1 and PDGFB." (PMID 22992343, 2012). "Hence, we proposed that immune-suppressive stroma could be vigorously promoted through a positive feedback loop of PDGFB signaling and IL6 signaling between cancer cells and CAFs." (PMID 37658364, 2023). "Platelet-derived growth factor β (PDGFB), which is provided by both cancer cells and non-cancerous stromal cells, is important for pericyte recruitment, and the interaction between PDGFB and PDGF receptor β (PDGFRB) on pericytes is responsible for mature-blood-vessel stabilization." (PMID 37029109, 2023). "Furthermore, PDGFB and PDGFR beta may also affect cancer growth and progression by directly acting on TME." (PMID 32855630, 2020). "We also noted high baseline expression of several other potential therapeutic targets including VEGFB, TGFB3, PDGFB/PDGFRB, FGFR1 and IGF1R in cancers that did not achieve pCR." (PMID 30967156, 2019).
infection (13 papers, 2009 to 2025). The state of being infected such as from the introduction of a foreign agent such as serum, vaccine, antigenic substance or organism. "By using ELISA, we found that the infection-caused upregulation of VEGFA, PDGFB, and ANGPTL4 in the brains of Egr-1−/− mice significantly decreased compared with that in WT mice." (PMID 38233877, 2024). "The lack of direct association between scarring progression and PDGFB in a model adjusting for infection could indicate that its upregulation is tightly correlated with the presence of infection." (PMID 31964744, 2020). "The Egr-1−/− mice were used to evaluate the contribution of Egr-1 to VEGFA, PDGFB, and ANGPTL4 production in response to the infection." (PMID 38233877, 2024). "The cells were infected with RCAS viruses expressing HRG, PDGFB-HA or eGFP (control) and subsequently stained for GFP, HRG and HA to determine infection efficiency." (PMID 20046875, 2009). "The ChIP-seq data revealed the significant Egr-1-binding peaks in the promoter region of VEGFA (chromosome 6 position 43,771,366 − 43,771,763), PDGFB (chromosome 22 position 39,243,987 − 39,244,220), and ANGPTL4 (chromosome 19 position 8,363,766-8,364,203) in the infection group." (PMID 38233877, 2024). "In scarring progressors PDGFB was upregulated 1.58-fold in response to infection, whereas it was upregulated 1.31-fold in nonprogressors." (PMID 31964744, 2020).
kidney disease (4 papers, 2012 to 2025). "PDGFB is a known mitogen for perivascular mesenchymal cells and is upregulated in kidney diseases." (PMID 40952790, 2025).
Cardiovascular Disease (3 papers, 2015 to 2024). "PDGFB have been implicated in the development of many pathological processes, such as cardiovascular disease." (PMID 39720896, 2024). "HMOX1, PDGFB, Ins, VEGF, and STAT5B are key nodes in the “Cardiovascular Disease, Lipid Metabolism, Molecular Transport” network and also interact with other DE genes." (PMID 25774290, 2015).
mitochondrial disease (1 paper, 2025). "Eight patients had IBGC (variants in SLC20A2, PDGFB, MYORG), 4 had mitochondrial disease (MT-TL1), and 2 had monogenic vascular conditions (GAL, MAP3K6)." (PMID 40947452, 2025).
PDGFB also shares sentences with these, for which no sentence is quoted: brainstem glioma (7 papers); Hyperglycemia (7); proliferative retinopathy (5); ischemia (4); cardiac hypertrophy (3); leukemia (3); adenocarcinoma (2); alveolar rhabdomyosarcoma (2); Basal ganglia calcification (2); bipolar disorder (2); brain cancer (2); colon cancer (2); endometrial stromal sarcoma (2); ependymoma (2); gastrointestinal stromal tumor (2); glomerulosclerosis (2); Granuloma (2); inflammation (2); inflammatory myofibroblastic tumor (2); ischemic stroke (2); lung adenocarcinoma (2); macular degeneration (2); mesenchymal neoplasm (2); metastatic disease (2); movement disorder (2); neurodegenerative disease (2); oligoastrocytoma (2); oral squamous cell carcinoma (2); Peritoneal Fibrosis (2); retinal detachment (2).
A further 130 diseases each share a sentence with PDGFB in 2 papers or fewer.